DOK3 (docking protein 3)
Diseases named in the same sentence as DOK3 in open-access papers (continued):
Sharing a sentence is not in itself a finding about the gene and the disease.
pneumonia (1 paper, 2020). An acute, acute and chronic, or chronic inflammation focally or diffusely affecting the lung parenchyma, caused by an infection in one or both of the lungs (by bacteria, viruses, fungi, or mycoplasma.). "These mentioned studies support the notion that VitB6 may activate AMPK to inhibit LPS‐induced macrophage activation and to prevent acute pneumonia by activating DOK3." (PMID 31970902, 2020). "In perspective, AMPK or DOK3 activator may be a new drug to prevent pneumonia." (PMID 31970902, 2020). "In vivo studies indicated that administration of VitB6 remarkably inhibited LPS‐induced both systemic inflammation and acute pneumonia in wild‐type mice, but not in DOK3−/− mice." (PMID 31970902, 2020).
retinoblastoma (1 paper, 2025). A malignant tumor that originates in the nuclear layer of the retina. "Moreover, in the high-ICI subgroup, CD83, HLA-DOA, IRF4, DOK3, and CXCR1 genes were also hypermethylated and thus associated with the presence of retinoblastoma." (PMID 41150792, 2025).
rheumatic diseases (1 paper, 2022). "A deeper understanding of the Dok3 signaling pathway could potentially reveal binding partners which can be targeted for future treatment of rheumatic diseases." (PMID 36788971, 2022).
tumor (9 papers, 2011 to 2026). "P.g. was implicated in OSCC recurrence by upregulating DOK3 protein in tumor-associated macrophages, potentially activating TNF and MAPK pathways." (PMID 40924302, 2025). "Given that immune cells infiltrating the microenvironment, a hallmark of inflammation, is known to affect tumor cell malignancy, we examined the impact of Dok-3 deficiency in Apc mice on inflammatory status of tumors." (PMID 36970719, 2022). "To assess how Dok-1/-2 deficiency enhances tumor growth but Dok-3 deficiency induces malignant conversion of benign tumors, we first evaluated expression levels of the Dok family genes in tumor epithelial cells of Apc mice." (PMID 36970719, 2022). "Together, these data indicate that Dok-3 deficiency is a tumor-extrinsic driving force of malignant progression in ApcMin/+ mice, providing a novel insight into microenvironments in tumor invasion." (PMID 36970719, 2022). "P.g. may contribute to OSCC recurrence by upregulating DOK3 in tumor-associated macrophages, activating TNF and MAPK signaling." (PMID 40924302, 2025). "In addition, transplantation of Dok-3–deficient bone marrow cells also induced malignant progression in ApcMin/+ mice, indicating a novel tumor cell–extrinsic mechanism underlying the malignant conversion of benign tumors." (PMID 36970719, 2022). "Furthermore, tumor cells in the center and invasion front of tumors retained expression of epithelial cell marker E-Cadherin in Apc/Dok3 mice, whose loss is a hallmark of EMT." (PMID 36970719, 2022). "Moreover, the Dok-3 loss–induced tumor invasion in ApcMin/+ mice required CD4+ and CD8+ T lymphocytes, but not B lymphocytes." (PMID 36970719, 2022). "Additionally, DOK3 has been shown to regulate junction proteins in tyrosine kinase signaling feedback loops and inhibit oncogenic pathways mediated by protein tyrosine kinases (PTKs), which are implicated in tumor development and progression." (PMID 39726593, 2024). "Thus, we transplanted Dok-3–deficient bone marrow cells, including hematopoietic stem cells that can systemically restore blood cells, into irradiated Apc mice to investigate the impact of Dok-3 loss in the bone marrow–derived stromal cells on tumor invasion." (PMID 36970719, 2022). "Parameters, including body mass index, clinical stage, recurrence, tumor differentiation, and P. gingivalis, DOK3, and M2-TAM immunoexpression levels, affected the prognosis of patients with OSCC (all P < 0.05)." (PMID 38671413, 2024). "DOK3 has also been demonstrated to regulate multiple signaling cascades related to cell proliferation, survival, invasion, and the tumor microenvironment, establishing its importance in cancer development and progression." (PMID 39726593, 2024). "Cox multivariate analysis indicated that clinicopathological parameters including BMI, clinical stage, recurrence, tumor differentiation, and P. gingivalis, DOK3, and M2-TAM immunoexpression levels affected the prognosis of patients with OSCC (all P < 0.05)." (PMID 38671413, 2024). "DOK3 acts as a key modulator of innate immune responses and may promote aggressive tumor behavior by shaping a macrophage-rich immune microenvironment." (PMID 40924302, 2025). "Several variables, including old age (≥ 60 year), tobacco smoking, poor periodontal condition, poor oral hygiene habits, severe dysphagia, larger tumor size (diameter ≥ 3 cm), advanced T stage, and death exhibited significant relationships with strong DOK3 expression (all P < 0.05)." (PMID 38671413, 2024). "Moreover, DOK3 has been shown to regulate signaling cascades involved in cell proliferation, survival, invasion, and tumor microenvironment regulation, establishing its role in cancer development and progression." (PMID 39726593, 2024). "Therefore, to identify lymphocyte populations essential for tumor invasion in Apc/Dok3 mice, we crossed Apc/Dok3 mice with CD4 and/or CD8-deficient mice to deplete CD4+ and/or CD8+ T cells." (PMID 36970719, 2022).
tumor (continued). "In addition, even in tumor organoid cells from Apc mice, the Dok-3 mRNA expression was undetectable." (PMID 36970719, 2022). "Interestingly, depletion of CD4+ or CD8+ T cells partially but significantly inhibited the tumor invasion observed in Apc/Dok3 mice." (PMID 36970719, 2022). "Interestingly, the loss of Dok-1/-2, the homologs of Dok-3, did not significantly affect malignant progression but rather enhanced tumor growth in Apc mice, indicating distinct roles of Dok-3 and Dok-1/-2." (PMID 36970719, 2022). "It was found that eight proteins (ADD2, DEF6, DOK3, ENO2, FMNL1, MICALL2, PARVG, and PSTPIP1) in KIRC cancer were more highly expressed in tumor tissues (100%), compared with normal tissues." (PMID 36428765, 2022). "Two of these, CBX7 and EGR1, have well-described tumor suppressor functions, and recently DOK4 family members (DOK1, DOK2, and DOK3) were identified as lung tumor suppressors." (PMID 21375733, 2011). "In summary, our study identified TOP2A, NCF4, FMNL1 and DOK3 as potential effective neoantigens for KIRC mRNA vaccine development, and patients with RIS2 tumor might benefit more from mRNA vaccination." (PMID 34872567, 2021). "In contrast, depletion of B or γδT lymphocytes had no impact on tumor invasion in Apc/Dok3 mice." (PMID 36970719, 2022). "Interestingly, the rate of invasive tumor occurrence in Apc/Dok3 mice lacking Rag1 (26%) was significantly lower than that in Apc/Dok3 mice (56%)." (PMID 36970719, 2022). "The consistent findings across different methodologies for DOK3 and PAPOLA emphasize their importance in shaping the immune landscape of various cancers, suggesting that these genes could be critical targets for therapeutic interventions to modulate tumor immunity." (PMID 39726593, 2024). "However, Dok-3 gene expression was undetectable in epithelial tumor cells and the transplantation of bone marrow cells lacking the Dok-3 gene–induced malignant conversion of epithelial tumor cells in ApcMin/+ mice, indicating a previously unrecognized tumor cell–extrinsic mechanism." (PMID 36970719, 2022). "In addition, aside from a suppression of small tumor (1.0 mm ≤ Φ < 2.0 mm) numbers observed in Apc/Dok3/Cd4/Cd8 mice compared with Apc/Dok3 mice, tumorigenesis in Apc/Dok3 mice was not significantly affected by depletion of any of the tested lymphocyte populations." (PMID 36970719, 2022). "However, we could not investigate the involvement of macrophages in tumor invasion in Apc/Dok3 mice, because we failed in our attempt to breed mice lacking Dok-3 and Csf1, the latter of which is critical for development of macrophages." (PMID 36970719, 2022).
cancer (6 papers, 2017 to 2024). A tumor composed of atypical neoplastic, often pleomorphic cells that invade other tissues. "Hence, it is becoming clear that Dok-3 is a complex adaptor associated with a plethora of diverse cellular processes implicated in health and diseases such as cancer, bone homeostasis, immune suppression, as well as anti-viral and -fungal immunity." (PMID 33133079, 2020). "Bioinformatics analyses were implemented to identify DOK3 as a key molecule and to appraise immunocyte infiltration using Gene Expression Omnibus and The Cancer Genome Atlas databases." (PMID 38671413, 2024). "DOK3, involved in immune signaling and apoptosis regulation, and PAPOLA, crucial for mRNA stability and linked to cancer, appear to be key components of the pathways through which SAH may parallel the effects observed in VaD." (PMID 39726593, 2024). "Furthermore, a pan-cancer analysis revealed that DOK3 and PAPOLA exhibit differential expression across various cancer types, reflecting their involvement in fundamental cellular processes like apoptosis and inflammation." (PMID 39726593, 2024). "Notably, DOK3 exhibits potential as an antitumor agent with anti-inflammatory and antioxidative properties, offering therapeutic benefits for both cancer and neuroinflammatory conditions." (PMID 39726593, 2024). "Collectively, these findings indicate that DOK3 overexpression exerts significant anti-inflammatory and protective effects by reducing apoptosis, inflammation, and oxidative stress, thus highlighting its potential therapeutic applications in inflammation-related diseases and cancer research." (PMID 39726593, 2024). "In our pan-cancer analysis, we examined the expression of DOK3 and PAPOLA across various cancer types." (PMID 39726593, 2024). "This comprehensive analysis provides a solid foundation for future studies to elucidate the precise mechanisms through which DOK3 and PAPOLA influence immune infiltration in cancer." (PMID 39726593, 2024).
benign tumors (1 paper, 2022). "Together, these findings demonstrate that CD4+ and CD8+ T cells, but not B and γδT cells, have an essential role in malignant progression of benign tumors in Apc/Dok3 mice, although the underlying mechanisms are yet unclear." (PMID 36970719, 2022). "Although it is unknown whether macrophages are involved in malignant conversion of benign tumors in ApcMin/+ mice lacking Dok-3, it might be possible that Dok-3–deficient macrophages play a role in the malignant progression by cooperating with CD4+ and CD8+ T cells." (PMID 36970719, 2022).
neurological disorders (1 paper, 2024). "Recent genomic studies have identified DOK3 as a potential risk locus for neurological disorders, likely due to its influence on microglial activation, a critical component of the central nervous system’s innate immune response." (PMID 39726593, 2024). "Recent studies have identified DOK3 as a potential risk locus for neurological disorders, potentially due to its impact on microglial activation." (PMID 39726593, 2024).
peripheral neuropathy (1 paper, 2020). A disorder affecting the peripheral nervous system. "Therefore, we posit that DOK3 plays a positive role in modulating inflammatory actions and microglial activation in response to peripheral neuropathy." (PMID 33281117, 2020).
DOK3 also shares sentences with these, for which no sentence is quoted: colorectal cancer (2 papers); inflammation (2); adenocarcinoma (1); Anxiety (1); Benign Epithelial Tumor (1); colorectal tumors (1); Familial adenomatous polyposis (1); infection (1); neurodegenerative disease (1); oral cancer (1); subarachnoid hemorrhage (1); ulcerative colitis (1); vascular dementia (1).